APOE (apolipoprotein E)
Diseases named in the same sentence as APOE in open-access papers (continued):
Sharing a sentence is not in itself a finding about the gene and the disease.
age-related macular degeneration (46 papers, 2007 to 2025). Age-related loss of vision in the central portion of the retina (macula), secondary to retinal degeneration. "Ocular disorders present some common hallmarks of neurodegenerative diseases and CNS pathologies extensively discussed by other authors, such as the connection between apoE metabolism and retinal inflammation linked to age-related macular degeneration." (PMID 36153580, 2022). "The role of amyloid in diseases other than AD such as age related macular degeneration may provide valuable new directions as Aβ and ApoE seem to be deposited in this disease but the ApoE ε4 allele is actually protective against this disease." (PMID 21416019, 2009). "APOE*ε2 is also associated with increased risk of certain neurological disorders such as post-traumatic stress disorder (PTSD), age-related macular degeneration (AMD), supranuclear palsy (PSP), and argyrophilic grain disease (AGD)." (PMID 33148290, 2020). "The APOE genotype also plays a role in age-related macular degeneration (AMD), where paradoxically APOE4 is protective." (PMID 30890171, 2019). "Strikingly, there is also evidence for APOE ε4 being protective in age-related macular degeneration, a classical age-related disease." (PMID 27457486, 2016). "Association between apolipoprotein E (APOE) and risk of age-related macular degeneration (AMD)." (PMID 21541275, 2011). "On the other hand, APOE ε2, with cysteine residues at both critical positions, is linked to a lower risk of Alzheimer’s but a heightened risk of type III hyperlipoproteinemia and age-related macular degeneration." (PMID 38674156, 2024). "For example, in ApoE−/− mice prone to accumulate lipids and remnants in the Bruch membrane characteristic of the early phase of age-related macular degeneration (AMD), [azaY4]-GHRP-6 decreased sub-retinal deposits and minimized macrophage infiltration within the subretinal space." (PMID 30360354, 2018). "These fascinating differences might help explain the APOE/cholesterol paradox of age-related macular degeneration." (PMID 29270905, 2017). "The CD subtype of AMD was significantly associated with current smoking as well as variants in the complement factor H (CFH), age-related maculopathy susceptibility 2 (ARMS2), complement factor B/complement component 2 (CFB/C2), complement component 3 (C3), and apolipoprotein E (APOE) genes." (PMID 22933840, 2012). "AD and age-related macular degeneration (AMD) share one of the main risk factors, such as age, and characteristics including the presence of deposits (Aβ plaques in AD and drusen in AMD); however, the role of apolipoprotein E isoforms in both pathologies is controversial." (PMID 35629270, 2022). "Complement regulation by FH on such lipoprotein particles could be potentially impaired in diseases characterized by immune deposits containing also apolipoprotein E, such as age-related macular degeneration (AMD) and dense deposit disease (DDD)." (PMID 30050540, 2018). "For example, how much variation is there in expression of the three genes involved in age-related macular degeneration (ARMD)—complement factor H (Cfh), the retina-specific ATP-binding cassette transporter (Abca4), and apolipoprotein E (Apoe)?" (PMID 19727342, 2009). "Lipid metabolism genes such as APOE, ABCA1, LIPC, and CETP play fundamental roles in the pathogenesis of age-related macular degeneration (AMD) by influencing lipid transport, cholesterol efflux, and lipoprotein remodeling within the retinal pigment epithelium (RPE) and Bruch’s membrane." (PMID 40331961, 2025). "In ophthalmology, the ApoE−/− model is most frequently used in neovascular age-related macular degeneration (AMD) experiments, but is not as widely used for studies of diabetic retinopathy." (PMID 20856927, 2010).
frontotemporal dementia (46 papers, 2006 to 2026). Frontotemporal dementia (FTD) comprises a group of neurodegenerative disorders, characterized by progressive changes in behavior, executive dysfunction and language impairment, as a result of degeneration of the medial prefrontal and frontoinsular cortices. "APOE was associated with severity at the trend level for the following FTLD related pathologies: Pick’s disease, PSP, and TDP-43." (PMID 32948752, 2020). "For example, in mice expressing a form of mutant human tau associated with frontotemporal dementia, co‐expression of human APOE4 led to a drastic increase in neurodegeneration compared to that seen with other APOE isoforms." (PMID 30394574, 2019). "We performed an updated meta-analysis to assess the role of the ε2/ε3/ε4 alleles of Apolipoprotein E gene (APOE) in frontotemporal lobar degeneration (FTLD)." (PMID 28487499, 2017). "Evidence from a meta-analysis of 28 case-control studies provided evidence for an association between the APOE E4 allele and frontotemporal lobar degeneration." (PMID 26830841, 2016). "A meta-analysis of 28 case–control studies provided evidence for an association between the APOE E4 allele and frontotemporal lobar degeneration." (PMID 24456740, 2014). "Location of the peaks of more hypoperfused areas in patients with Frontotemporal Lobar Degeneration carrying Apolipoprotein E ε4 allele." (PMID 16930470, 2006). "APOE gene polymorphism is known to be associated with Pick's disease." (PMID 24312462, 2013). "The presence of truncated apoE within Pick bodies suggests a broader role of apoE beyond AD and raises the question as to whether this protein contributes to pathogenesis associated with Pick's disease." (PMID 24312462, 2013). "To determine if apoE is cleaved in Pick's disease, we analyzed five cases by immunohistochemistry using our novel, in house antibody that detects amino-terminal cleavage fragments of apoE (termed nApoECF antibody)." (PMID 24312462, 2013). "Taken together, these results demonstrate the presence of apoE amino-terminal fragments in the Pick's disease brain." (PMID 24312462, 2013). "In contrast, APOE ε2 has been suggested to increase the risk of frontotemporal dementia in patients with ALS, whereas the ε4 allele does not appear to confer a similar effect." (PMID 41149812, 2025). "To perform an immunohistochemical analysis utilizing the nApoECF antibody, we examined 5 available cases of Pick's disease in which the APOE genotype of 3/3 was identified in three of the five cases, while the APOE genotype of the other two cases was not available." (PMID 24312462, 2013). "Further studies examining the role of apoE, tau and any relation to specific proteases should shed light on whether apoE also contributes to disease pathogenesis in Pick's disease." (PMID 24312462, 2013). "The purpose of the present study was to examine whether amino-terminal fragments of apoE can be documented in Pick's disease." (PMID 24312462, 2013). "Therefore, we sought to determine a potential role of apoE in Pick's disease by examining for the presence of fragmented apoE utilizing an in house antibody designed to detect the amino-terminal fragment of apoE." (PMID 24312462, 2013). "However, whether apoE4 or other isoforms of apoE play any role in the etiology of Pick's disease is currently unknown." (PMID 24312462, 2013). "Blood GFAP levels increase with aging and are further elevated in females, MCI, AD, Parkinson's disease, and frontotemporal dementia (FTD) but are not affected by the APOE ε4 allele." (PMID 40145342, 2025). "The inheritance of ApoE ε4 is related to late-onset familial and sporadic AD, and ApoE ε4 increases the risk of developing CAA and AD, while ApoE ε2 lowers the risk of frontotemporal dementia (FTD) in a very small cohort." (PMID 36817952, 2023).
frontotemporal dementia (continued). "APOE’s role in tau pathology has drawn much interest both within AD research and among researchers studying related tau-related diseases such as FTD (frontotemporal dementia), CTE (chronic traumatic encephalopathy), and CBD (corticobasal degeneration)." (PMID 37445986, 2023). "Some of these ligands that are especially disease relevant include ApoE, Aβ, and the most recently discovered interactor, TDP-43, which is a protein that can become pathologically accumulated in neurodegenerative diseases, such as frontotemporal dementia (FTD) and ALS." (PMID 36768798, 2023).
viral infection (46 papers, 2010 to 2025). "Two ε4 alleles of APOE-ε4 confers a loss in gene activity that can defend against viral infections leading to disruption of cerebral blood vessels and increased inflammatory activity." (PMID 37508898, 2023). "The APOE-ε4 allele is a well-established genetic risk factor for AD but has also been shown to influence susceptibility to viral infections." (PMID 39483362, 2022). "Previous studies which analyzed AD patients who were positive for herpes simplex virus type I (HSV-I) found a higher frequency of APOE 4ε, with an odds ratio (OR) value of 16.8, indicating that APOE 4ε enhances susceptibility to viral infection." (PMID 36291338, 2022). "ApoE expression has also been found to affect susceptibility to several viral diseases, including Hepatitis C and E, but its effect on the life cycle of HIV-1 remains obscure." (PMID 30496280, 2018). "APOE, for example, influences susceptibility to certain viral infections, HSV-1 viral load in the brain, and the innate immune response." (PMID 29559905, 2018). "APOE gene also appears to be involved in chronic infections and it is important to note that the APOE gene is a well known susceptibility factor for several virus infections." (PMID 25516763, 2014). "APOE also influences susceptibility to parasitic, bacterial, and viral infections." (PMID 40625502, 2025). "Thus, our tests cannot exclude the possibility that virus infection modifies and re-arranges membrane association of ApoE in a way that facilitates final release." (PMID 40295730, 2025). "It is possible that severe and chronic peripheral inflammation caused by persistent bacterial or viral infection may enhance certain genetic vulnerabilities for AD, including those conferred by APOE ε4, as well as particular SPI1 and CD33 genotypes." (PMID 36550123, 2022). "ApoE is associated with the susceptibility to general viral infections." (PMID 33800954, 2021). "This might be particularly evident in carriers of the ε4 variant of the apolipoprotein E (ApoE) gene, the most strongly established genetic risk for sporadic AD that also modulates cardiovascular diseases and cellular processes related to viral infections." (PMID 34149394, 2021). "Many studies have shown that apoE is also implicated in viral infections." (PMID 28660014, 2017). "Neutralizing ApoE or removing its cell-surface receptors attenuates entry of HCV and HBV, further implicating ApoE in supporting these viral infections." (PMID 40439406, 2025). "Recent studies have revealed that ApoE plays important roles during viral infections and pathogenesis." (PMID 40295730, 2025). "In this work, we investigated the potential influence of the human protein ApoE on primary virus infection, at a molecular level." (PMID 40295730, 2025). "Despite the existing studies of ApoE in these diverse viral infection models, the role of ApoE in gammaherpesvirus infection remains poorly understood." (PMID 40439406, 2025). "HSV1 growth was also tested on SH-SY5Y cells where ApoE was present prior to and kept during the period of virus infection except for the 1 h inoculation." (PMID 40295730, 2025). "In the discussion, APOE and TREM2 have been implicated in susceptibility to various viral infections (such as HIV and SARS-CoV-2)." (PMID 37962454, 2024). "For example, meta-analyses indicate associations between AD and viral infections with HSV-1, especially in individuals with the APOE ε4 allele." (PMID 38535583, 2024). "ApoE is dramatically involved in the life cycle and pathogenesis of viral infections, such as chronic hepatitis C virus (HCV), hepatitis B virus (HBV), herpes simplex virus type-1 (HSV-1), and HIV infections." (PMID 38002250, 2023). "Notable, recently Xu’s group also detected the association between ApoE and ACE2, and this interaction exhibits an inhibitory effect of SARS-CoV-2 pseudo-viral infection." (PMID 36759834, 2023).
viral infection (continued). "The presence of ApoE on SARS‐CoV‐2 viral particles provides an opportunity to block viral infection using ApoE neutralizing antibodies." (PMID 37822714, 2023). "Current studies have been documenting the influence of different isoforms of ApoE on viral infections, such as human immunodeficiency virus (HIV), herpes virus (HSV-1), and chronic hepatitis C virus (HCV)-induced liver disease." (PMID 35359998, 2022). "Expression of these genes is associated with movement (MMP9, SPP1, ALCAM, and others), viral infection (APOC1, LGALS3, CD63, and others), and recruitment of phagocytes (APOE, CHI3L1, LGALS3, and others)." (PMID 32723919, 2020). "Because ApoE is versatile and is polymorphic within the population, in addition to increasing the complexity of viral infection, the long-term hijacking and utilization of ApoE by HCV also leads to more complex pathological results." (PMID 31027190, 2019). "ApoE-ε4 was observed to be more frequent in diseases in which innate immunity plays a role, including AD, and, more recently, viral infection." (PMID 31455413, 2019). "The apoE isoforms were differently correlated with viral infections, influencing the viral cell entry and infection progression." (PMID 28660014, 2017). "Our hypothesis describes a set of gene upstream of the APOE locus on chromosome 19 spanning from CEACAM-19 to APOE that may constitute a gene cluster of susceptibility for AD by affecting different mechanism involved in virus entrance or resistance to virus infection." (PMID 21156047, 2010). "Recently, the emerging relationship between APOE and viral infection has been reported." (PMID 38707479, 2024). "However, the current evidence remains insufficient for establishing a clear association between APOE or TREM2 as predictive factors for AD and specific viral infections." (PMID 37962454, 2024). "Whether ApoE affects viral infection through interaction with viruses or receptors is currently unclear." (PMID 36759834, 2023). "Many of these hypotheses have been generated based on previous studies investigating the impact of ApoE isoform on other viral infections, such as with hepatitis C or HIV-1." (PMID 33800954, 2021). "It is thought the ApoE isoform can alter the severity of viral infection." (PMID 33800954, 2021). "Exactly how different apoE isoforms may affect viral infection in the body and CNS remains unclear, which makes it difficult to delineate contributions from viral infection to AD vs those from different apoE isoforms." (PMID 30603085, 2018). "PKR is activated during viral infection, including that of herpes simplex virus type 1 (HSV1), a virus suggested to be implicated in the development of AD, acting when present in brains of carriers of the type 4 allele of the apolipoprotein E gene." (PMID 21738672, 2011). "Interestingly, ApoE exhibits pleiotropic roles during viral infection." (PMID 40439406, 2025). "The effects of viral infections might be apolipoprotein E (apoE) isoform-dependent." (PMID 39660133, 2024). "Given prior evidence of the role of Herpes simplex virus 1 (HSV-1) in AD pathogenesis in APOE-ε4 carriers, one avenue of experimentation might be to test the viability of viral infection (e.g. HSV-1) in cell lines from individuals with the A versus G allele at 10398." (PMID 37369829, 2023). "Therefore, it cannot be completely ruled out that ApoE polymorphisms affect the risk of viral infection by interfering with the interaction of the spike protein with the ACE2 receptor." (PMID 36759834, 2023). "Alternatively, APOE alleles may modulate viral entry into the brain, whereby viral infection would be a consequence of APOE status rather than a causal factor for AD onset." (PMID 30603085, 2018). "In the current study, we identify APOE as a negative regulator for SARS-CoV-2-induced inflammatory response and SARS-CoV-2 pseudo-virus infection." (PMID 35915083, 2022).
viral infection (continued). "In hepatitis C viral infection, the virus hijacks this pathway via interaction with apolipoprotein E for cell entry, while heparan sulfate proteoglycans are required for cellular binding of the hepatitis E virus ORF2 capsid protein and for viral infection." (PMID 32512929, 2020). "As expected, TNF-α, previously shown to inhibit apoE in macrophages, led to a similarly reduced production as did IFN-α, a cytokine normally induced by viral infection." (PMID 24244577, 2013). "Analyses of gene expression related to lipid metabolism in various virus-infected tissues revealed decreased expression of APOE and Lp-PLA2, which could be related to the dysfunction induced by viral infection." (PMID 39872814, 2024).